SHBG (sex hormone binding globulin)
Diseases named in the same sentence as SHBG in open-access papers (continued):
Sharing a sentence is not in itself a finding about the gene and the disease.
diabetes (continued). "RBC (p = 0.012), AlAt, C-peptide (both p < 0.001) were higher whereas SHBG (p = 0.002), adiponectin and IGFBP-1 (both p < 0.001) were lower in individuals with prediabetes/diabetes in comparison with individuals with normal glucose tolerance." (PMID 35439985, 2022). "Diabetes also promotes the production of IGF-1 in the liver and inhibits the secretion of sex hormone-binding globulin (SHBG) and IGF-binding protein (IGFBP)." (PMID 33842335, 2021). "The observed relationship was robust and independent of potential confounders such as age, race, smoking status, BMI, hypertension, diabetes, estimated GFR, total cholesterol, total testosterone, SHBG, and androstenedione." (PMID 31511566, 2019). "When compared with men who remained robust or prefrail, those whose frailty status deteriorated over follow-up (n = 426) were older and had lower baseline BMI, but higher SHBG, LH, and FSH hormones and a higher prevalence of diabetes and CVD." (PMID 29186457, 2018). "Although the results for the effect of maternal diabetes were unstable, previous studies observed decreased serum sex hormone binding globulin (SHBG) levels and increased insulin levels in umbilical cord blood in pregnant women with diabetes." (PMID 25798927, 2015). "In both men and women without diabetes mellitus SHBG concentrations were previously shown to be, independently from sex steroids, inversely correlated with glycated hemoglobin." (PMID 39014506, 2024). "SHBG plasma concentration, independently from sex steroids, is inversely correlated with glycosylated hemoglobin in both men and women without diabetes mellitus." (PMID 39014506, 2024). "After adjustment for insulin therapy, the difference in testosterone levels (including total testosterone, bioavailable testosterone, and sex hormone-binding globulin) disappeared in all patients with diabetes, regardless of gender." (PMID 37900148, 2023). "Serum concentrations of total and free testosterone and SHBG significantly decreased from no diabetes and prediabetes to diabetes group in both males and females." (PMID 37264434, 2023). "The chosen studies were stratified according to the factors of study design, location, patient types, age, follow-up duration, and adjustment for race, body mass index (BMI), hypertension, diabetes, creatinine, C-reactive protein (CRP) as well as sex hormone binding globulin (SHBG)." (PMID 36124237, 2022). "Although the specific role of SHBG in the glucose metabolism is not clear yet, recent studies have implicated that the alterations in normal sex steroids physiology may have a role in the glucose homeostasis and low SHBG levels may precede the development of type-2 diabetes mellitus." (PMID 34458674, 2021). "Consumption of a diet high in monosaccharides particularly fructose, can reduce serum SHBG levels by about 80% in people without diabetes, and by about 40–50% among those with diabetes." (PMID 29995902, 2018). "In this study of a Swedish adult population, subjects with T1D had significantly higher levels of SHBG than subjects without diabetes or with T2D." (PMID 23781314, 2013). "When men and women were considered separately, SHBG levels were higher in subjects with T1D than in subjects without diabetes or those with T2D." (PMID 23781314, 2013). "Subjects with T2D had significantly lower levels of SHBG than subjects without diabetes when age adjusted analysis was computed separately for men and women." (PMID 23781314, 2013). "Several factors can influence this relationship, including the presence or absence of diabetes (e.g., T2D), the duration of hyperglycemia, the levels of leptin or adiponectin from the adipose tissue, and the impact of high insulin levels on sex hormone-binding globulin (SHBG)." (PMID 38731059, 2024).
diabetes (continued). "Subgroup analysis demonstrated that the inverse association between total testosterone and the risk of all-cause death remained significant regardless of factors such as age, race, body mass index, diabetes, hypertension, C-reactive protein, creatinine, and sex hormone binding globulin." (PMID 39014506, 2024). "The three studies used for the diabetes comparison represent the largest candidate protein characterisations of type 2 diabetes to date and the top markers identified included aminoacylase-1 (ACY-1), sex hormone-binding globulin (SHBG) and growth hormone receptor (GHR)." (PMID 35023833, 2022). "Furthermore, lower SHBG levels were reported to be associated with higher fasting blood glucose levels among women with recent GDM, a high-risk population for diabetes, and this association was independent of potential confounders." (PMID 28279160, 2017). "In logistic regression analyses, after adjusted for age, sex, duration of diabetes, smoking status, and alcohol use, the ORs and 95%CI for presence of MS was 2.26 (95%CI 1.91–2.68) and for presence of NAFLD was 6.36 (95%CI 4.87–8.31) with per one SD decrease in serum SHBG (both P < 0.001)." (PMID 29109457, 2017). "This may partly explain our results of significantly increased SHBG levels among postmenopausal women without dysglycaemia, while those with prediabetes or diabetes have only marginally increased SHBG levels." (PMID 27898110, 2016). "Third, we did not measure the SHBG and free testosterone levels in the present study while considering the cost, which may limit the investigation on the relationship between testosterone and UA in patients with diabetes." (PMID 32153501, 2020). "In cases without diabetes (n = 22) a significant correlation was observed between the HOMA-R (r = -0.586, p = 0.004) and the fasting insulin levels (r = -0.650, p = 0.001) on the one hand and the serum SHBG levels on the other." (PMID 39014506, 2024). "Since in all the studies included with age adjusted, the prognostic significance of circulating testosterone might be independent of race, BMI, age, hypertension, diabetes, creatinine, CRP, and SHBG." (PMID 36124237, 2022).
hyperandrogenism (173 papers, 2009 to 2026). Excessive secretion of androgens from the adrenal glands or gonads. "Serum MG53 is reduced in PCOS and is associated with SHBG and features related to androgen excess and ovarian morphology." (PMID 41974999, 2026). "Vitamin D deficiency is associated with decreased levels of SHBG (sex hormone-binding globulin), resulting in greater circulating levels of free testosterone, thereby contributing to hyperandrogenism." (PMID 41295220, 2025). "Elevated insulin levels stimulate androgen production in the ovaries and reduce sex hormone-binding globulin (SHBG), leading to hyperandrogenism—a hallmark feature of PCOS." (PMID 40281834, 2025). "It is thought that OSA is linked to hyperandrogenism primarily via modulation of SHBG production in the liver." (PMID 39996383, 2025). "This weight loss leads to increased sex hormone binding globulin (SHBG) and decreased testosterone levels, thereby alleviating symptoms of hyperandrogenism." (PMID 38399581, 2024). "Studies have shown that excessive concentrations of insulin can cause hyperandrogenism by promoting ovarian and adrenal glands to secrete androgen, inhibiting SHBG synthesis in the liver." (PMID 31885557, 2019). "Given the important role of SHBG in the incidence of PCOS-induced hyperandrogenism, it is likely to be a susceptibility gene in PCOS." (PMID 30944702, 2019). "Positive correlation of hyperandrogenism with (TAAAA)n polymorphism in SHBG gene promoter has been confirmed." (PMID 30944702, 2019). "Because of the inverse relationship between weight and sex hormone binding globulin, Acarbose increases this globulin through weight loss and increases insulin sensitivity and decreases LH and hyperandrogenism." (PMID 27157179, 2016). "After screening 2445 records based on titles and abstracts and 208 full‐texts, 24 articles (corresponding to 19 unique studies) met the eligibility criteria and reported data on the associations between sex hormones, SHBG or hyperandrogenism and sleep problems and thus, included in the review." (PMID 39996383, 2025). "However, our study showed that compared with the control group, the level of SHBG decreased in EH group, and hyperandrogenism is an independent risk factor for EH." (PMID 37149578, 2023). "We studied whether androgen excess and low sex hormone‐binding globulin (SHBG) measured in early pregnancy are independently associated with fasting and post‐prandial hyperglycaemia, gestational diabetes (GDM), and its severity." (PMID 36484476, 2023). "Low plasma SHBG in pregnancy was also associated with hyperandrogenism." (PMID 36733795, 2022). "Additionally, hyperandrogenism is associated with HS as a result of low SHBG concentrations with a correlated elevation of free testosterone." (PMID 34371959, 2021). "Furthermore, it has been shown that in obese women SHBG affinity for T is lowered, potentially having a compound effect on IR-caused hyperandrogenism." (PMID 34572562, 2021). "SHBG concentrations decrease following menopause but increase during the sixth decade of life, and low serum levels of SHBG have been associated with hyperandrogenism and endometrial cancer." (PMID 33329395, 2020). "Abnormalities in SHBG levels, caused by a number of metabolic abnormalities, result in abnormal hormone levels and direct clinical presentation, such as increased risk of developing hyperandrogenism in obese female populations or abnormal semen composition in men with overweight." (PMID 40427034, 2025). "Additionally, weight loss may help reverse hyperandrogenism in patients with PCOS by increasing SHBG levels, thereby lowering circulating androgen levels." (PMID 39459443, 2024). "Whereas the other biochemical hyperandrogenism parameters including total testosterone, free testosterone, free androgen index, sex hormone binding globulin (SHBG) are negatively associated with FG scores, although the effects of simvastatin or metformin on SHBG is akin to DHEAS." (PMID 34930305, 2021).
hyperandrogenism (continued). "In lean PCOS, elevated SHBG levels can potentially reduce the availability of free androgens, thereby alleviating the symptoms of hyperandrogenism to some extent." (PMID 41163678, 2025). "These reductions, as well as an increase in SHBG levels, are clinically significant as they indicate an improvement of hyperandrogenism." (PMID 40944281, 2025). "Studies that examined serum sex hormones, SHBG or hyperandrogenism with sleep disorders and/or sleep disturbances in PCOS were eligible." (PMID 39996383, 2025). "This interaction is of interest because of the relative difference in the driver of androgen excess in each subtype (primary androgen excess versus low SHBG)." (PMID 41180187, 2025). "The consequent reduction in SHBG elevates free testosterone bioavailability, exacerbating clinical manifestations of hyperandrogenism." (PMID 41427050, 2025). "It was found that elevated LH levels increase free testosterone by reducing serum SHBG, thus amplifying hyperandrogenism and menstrual irregularity." (PMID 40806019, 2025). "abdominal obesity changes the clearance and deposition of fat-soluble androgen and increases hyperandrogenism by lowering sex hormone-binding globulin (SHBG) levels." (PMID 40410881, 2025). "Decline in serum SHBG levels resulted in increased serum levels of active androgens and hyperandrogenism presentation in overweight and obese women." (PMID 40427034, 2025). "This is particularly relevant for women, in whom hypo-SHBG states are predictive of hyperandrogenism, ovulatory dysfunction, and infertility, as well as increased long-term risk for breast and endometrial cancer." (PMID 41586225, 2025). "Reduced SHBG allows free testosterone to accumulate, shifting the hormonal balance towards hyperandrogenism, a key feature of PCOS." (PMID 40650160, 2025). "A previous meta‐analysis suggested that women with PCOS and lower SHBG levels, especially for those with high body mass index (BMI), were more likely to have hyperandrogenism, metabolic issues and infertility." (PMID 39996383, 2025). "Insulin also indirectly influences the prevalence of hyperandrogenism by decreasing the liver’s production of sex hormone-binding globulin (SHBG), thus increasing serum androgen levels." (PMID 40076815, 2025). "The liver manufactures SHBG, which as a sex hormone transporter can be utilized to gauge hyperandrogenism." (PMID 38790905, 2024). "SHBG is low in hyperandrogenic states and calculating free androgen index requires measuring SHBG which acts as a proxy for free T. Free T was comparable to A4 in detecting hyperandrogenism in women with PCOS." (PMID 38435886, 2024). "Future research should aim to clarify the effect of probiotics and synbiotics on SHBG and clinical symptoms such as hirsutism to better understand the therapeutic potential of these interventions in managing hyperandrogenism in PCOS." (PMID 39599701, 2024). "Elevated insulin levels also promote excessive ovarian androgen secretion and decrease the synthesis of SHBG in the liver, further exacerbating hyperandrogenism." (PMID 39351128, 2024). "Hyperandrogenism in postmenopausal women is frequently observed because of a relative physiologic rise of androgens due to a decline in estrogens and an increase in sex hormone-binding globulin." (PMID 39803098, 2024). "As a result, hyperandrogenism lowers the levels of sex hormone-binding globulin (SHBG), leading to an increased concentration of free testosterone." (PMID 39459443, 2024). "Another aspect of hyperandrogenism that has implications in laboratory measurement is that of sex hormone binding globulin (SHBG)." (PMID 38435886, 2024). "The concentration of SHBG, a pivotal globulin that binds estrogen and androgens and regulates their biological activities, is used as an indicator of hyperandrogenism in women with PCOS." (PMID 39201400, 2024).
hyperandrogenism (continued). "Insulin and androgens restrict the liver from producing and releasing SHBG; thus, hyperandrogenism in people with PCOS results in low serum SHBG, which further increases testosterone levels." (PMID 38790905, 2024). "Our own investigations have confirmed that augmented abdominal adiposity in PCOS women is associated with IR, diminished sex-hormone-binding globulin (SHBG) levels, hyperandrogenism, and low-grade inflammation (elevated interleukin-18 (IL-18])." (PMID 38275393, 2024). "The PCOS rats demonstrated androgen excess, multiple ovarian cysts, elevated anti-mullerian hormone and leptin and decreased SHBG, adiponectin and 17-β estradiol with corresponding increase in ovarian transforming growth factor-β1." (PMID 38561673, 2024). "PCOS is considered a relatively mild form of hyperandrogenism since circulating levels of testosterone usually are within the upper normal female range, whereas SHBG is low, resulting in increased levels of free and bioavailable testosterone." (PMID 36409990, 2023). "SHBG is usually used as a measure to judge the severity of hyperandrogenism, because it exhibits high affinity for testosterone." (PMID 37293501, 2023). "They positively influence menstrual cycle regularity, carbohydrate metabolism, and the clinical and laboratory symptoms of hyperandrogenism (e.g., free testosterone, total testosterone, SHBG)." (PMID 36703143, 2023). "Reduced SHBG levels lead to increased free testosterone levels worsening the symptoms of hyperandrogenism." (PMID 36703143, 2023). "IR exacerbates hyperandrogenism by stimulating androgen synthesis and inhibiting sex hormone-binding globulin (SHBG)." (PMID 37525285, 2023). "It is thought to underpin hyperandrogenism by acting synergistically with luteinizing hormone (LH) on ovarian steroidogenic enzymes and on sex hormone-binding globulin (SHBG) production by the liver." (PMID 36429632, 2022). "The meta-analysis also suggested that women with PCOS and lower SHBG levels were more likely to have hyperandrogenism, metabolic issues and infertility." (PMID 36457554, 2022). "In our study, we assessed hyperandrogenism by measuring the concentration of free testosterone, SHBG, FAI, and androstenedione." (PMID 35813634, 2022). "Modest weight loss (5–10% of initial body weight) has been shown to lead a rise in SHBG, a reduction of circulating androgens and clinical manifestations of hyperandrogenism, an improvement in ovarian function, and a higher pregnancy rate." (PMID 36009471, 2022). "With respect to biochemical hyperandrogenism, SHBG, which impacts the free androgen status, was similar in women with and without PCOS." (PMID 35535684, 2022). "The FAI is an indicator of the TT level by SHBG adjustment and was the best index for representing hyperandrogenism in PCOS patients in our study." (PMID 33583431, 2021). "Secondly, insulin decreases hepatic production of SHBG, the plasmatic carrier of sex steroids, thus increasing the amount of circulating free testosterone, which is responsible for the clinical signs of hyperandrogenism (hirsutism, acne and alopecia)." (PMID 34071499, 2021). "No less important is that the mixed ketogenic diet resulted in an increase in albumin and SHBG, both free testosterone binding proteins, with a consequent reduction in bioactive free testosterone, thus contributing to a further improvement of hyperandrogenism." (PMID 34886216, 2021). "The biological activity of androgens is also determined by free testosterone, and therefore investigation of SHBG levels is essential in assessing hyperandrogenism; in PCOS patients, one of the reasons for low serum SHBG levels is hyperandrogenemia." (PMID 34311759, 2021). "SHBG binds to free androgens and lowers free androgen levels, then reducing hyperandrogenism and IR." (PMID 34311759, 2021). "IR exacerbates hyperandrogenism through increased ovarian androgen production and decreased sex hormone-binding globulin (SHBG) production." (PMID 32782010, 2020).